GAGE12C (G antigen 12C)
Synonyms: GAGE-12B; OTTHUMG00000024144
Gene: Protein-coding gene on chromosome X (49,532,177 to 49,539,539, forward strand). Ensembl gene ENSG00000237671.
Subcellular location (Human Protein Atlas): Plasma membrane; Cytosol; Golgi apparatus
Gene Ontology:
Molecular function: protein binding
Homologues: Orthologues: chimpanzee GAGE10 (82% identical). Paralogues in human: GAGE12D (100% identical), GAGE12E (100% identical), GAGE12F (99% identical), GAGE12G (99% identical), GAGE12H (99% identical), GAGE1 (97% identical), GAGE12J (97% identical), GAGE13 (97% identical), GAGE2A (96% identical), GAGE2E (93% identical), GAGE10 (90% identical), PAGE1 (52% identical), and 10 more.